TCF21 (transcription factor 21)
Description:
Involved in epithelial-mesenchymal interactions in kidney and lung morphogenesis that include epithelial differentiation and branching morphogenesis. May play a role in the specification or differentiation of one or more subsets of epicardial cell types.
Synonyms: bHLHa23; POD1
Tractability: No criterion of Open Targets' tractability assessment is met for any kind of drug.
Gene: Protein-coding gene on chromosome 6 (133,889,113 to 133,895,553, forward strand). Ensembl gene ENSG00000118526.
Subcellular location: Nucleus
Subcellular location (Human Protein Atlas): Nucleoplasm
Gene Ontology:
Molecular function: bHLH transcription factor binding; DNA-binding transcription repressor activity, RNA polymerase II-specific; protein binding; sequence-specific double-stranded DNA binding; DNA-binding transcription activator activity, RNA polymerase II-specific; DNA-binding transcription factor activity, RNA polymerase II-specific; E-box binding; nuclear androgen receptor binding; RNA polymerase II transcription regulatory region sequence-specific DNA binding; DNA-binding transcription factor activity; histone deacetylase binding; protein dimerization activity
Biological process: negative regulation of transcription by RNA polymerase II; branching involved in ureteric bud morphogenesis; branchiomeric skeletal muscle development; bronchiole development; developmental process; diaphragm development; embryonic digestive tract morphogenesis; epithelial cell differentiation; gland development; glomerulus development; kidney development; lung alveolus development; lung morphogenesis; lung vasculature development; metanephric glomerular capillary formation; metanephric mesenchymal cell differentiation; morphogenesis of a branching structure; negative regulation of androgen receptor signaling pathway; positive regulation of transcription by RNA polymerase II; regulation of transcription by RNA polymerase II; reproductive structure development; respiratory system development; roof of mouth development; Sertoli cell differentiation; sex determination; and 3 more
Cellular component: nucleoplasm; nucleus; chromatin; transcription regulator complex
Genetic constraint (gnomAD): Loss-of-function variants: 3 observed, 14.64 expected, observed/expected ratio (o/e) 0.2, 90% interval 0.092 to 0.53. The upper end of that interval is the gene's LOEUF score, 0.53, which puts it in group 2 of 6, group 1 being the genes least tolerant of losing a copy. Missense variants: 181 observed, 253.58 expected, observed/expected ratio (o/e) 0.71, 90% interval 0.63 to 0.81. Synonymous variants: 92 observed, 110.08 expected, observed/expected ratio (o/e) 0.84, 90% interval 0.7 to 0.99.
Gene-disease validity (ClinGen):
ClinGen rates the evidence that TCF21 causes each of these diseases.
congenital heart disease (inheritance undetermined): No Known Disease Relationship. A heart disease that is present at birth.
Homologues: Orthologues: chimpanzee TCF21 (100% identical), guinea pig TCF21 (99% identical), macaque TCF21 (99% identical), rabbit TCF21 (99% identical), pig TCF21 (99% identical), dog TCF21 (98% identical), rat Tcf21 (97% identical), mouse Tcf21 (96% identical), tropical clawed frog tcf21 (88% identical), zebrafish tcf21 (75% identical), Drosophila melanogaster HLH54F (32% identical), Drosophila melanogaster CG33557 (22% identical), and 3 more. Paralogues in human: MSC (63% identical), TCF15 (31% identical), TCF24 (30% identical), SCX (29% identical), TCF23 (26% identical), TWIST2 (25% identical), HAND2 (25% identical), TWIST1 (24% identical), HAND1 (22% identical), FIGLA (22% identical), PTF1A (22% identical), BHLHA9 (20% identical), and 1 more.
Diseases named in the same sentence as TCF21 in open-access papers:
TCF21 is named in the same sentence as 97 diseases in open-access papers, as found by Europe PMC text mining. Sharing a sentence is not in itself a finding about the gene and the disease. The quoted sentences say what the papers report.
lung carcinoma (36 papers, 2008 to 2025). "When Sphk2 was knockdown in p16-deficient lung cancer cells, induction of caspase-3-dependent apoptosis occurred through the activation of transcription factor 21 (TCF21)." (PMID 39063108, 2024). "Here, we validated the diagnostic value of TCF21 in lung cancer by showing that TCF21 downregulation is a characteristic of lung cancer patients with poor survival." (PMID 27894084, 2016). "In summary, we hereby report that TCF21 is a putative diagnostic and therapeutic target in lung cancer." (PMID 27894084, 2016). "We also show that downregulation of TCF21 is associated with poor survival of lung cancer patients." (PMID 27894084, 2016). "Clearly, low TCF21 expression is associated with poor survival of lung cancer." (PMID 27894084, 2016). "It is possible that TCF21 downregulation is associated with the drug resistance of lung cancer." (PMID 27894084, 2016). "Thus, detection of the methylated TCF21 levels is a promising approach to determine lung cancer risk, in order to improve the clinical management of lung cancer." (PMID 27894084, 2016). "Previously, downregulation of TCF21 was demonstrated to be associated with poor survival in clear cell renal cell carcinoma, urological cancer, head and neck cancer, gastric cancer and lung cancer." (PMID 27894084, 2016). "However, such an approach might also put the patient at increased risk for head and neck and lung cancer, as TCF21 is a potent tumor suppressor gene that is frequently mutated or silenced in cells of these tumors." (PMID 23874238, 2013). "TCF21 has been confirmed to play tumor suppressor effect in lung cancer, but its mechanism in LUSC is still unclear." (PMID 40226362, 2025). "Curcumin induces anti-lung-cancer effects by upregulating exosomal transcription factor 21 (TCF21) expression and downregulating DNA (cytosine-5)-methyltransferase 1 (DNMT1), i.e., a TCF21 suppressor." (PMID 38892270, 2024). "The experimental results revealed that the expression of TCF21 was decreased in lung cancer cells and TAM." (PMID 37765264, 2023). "This study demonstrated that TCF21 and Notch4 were greatly down-regulated in lung cancer cells and TAMs, and Notch4 was the downstream target gene of TCF21." (PMID 37765264, 2023). "The application of genomic scanning to obtain DNA methylation profiling in the region of recurrent loss of heterozygosity at human chromosome 6q23-q24 identified the TCF21 gene in lung cancer." (PMID 33729392, 2021). "Functional studies showed that LINC00163 induces TCF21 expression by recruiting ARID1A to the TCF21 promoter, suggesting a mechanism of lung cancer progression." (PMID 33729392, 2021). "Research has indicated that circRNA_100395 (circ_100395) is downregulated in lung cancer tissues and can inhibit lung cancer progression by regulating miR-1228/TCF21 pathway." (PMID 33842488, 2021). "Here, we found the strongest inactivation of EGR1 binding motif within the TCF21, an epigenetically regulated tumor suppressor gene in lung cancer." (PMID 33859751, 2021). "Hsa_circ_100395 has been shown to regulate TCF21 through miR-1228 to inhibit the malignant behavior of lung cancer, providing a new possible mechanism for the progression of lung cancer." (PMID 34252882, 2021). "For example, it had been reported that hsa_circ_100395 regulated lung cancer cell proliferation, migration and invasion through modulating the miR-1228/TCF21 pathway." (PMID 32196072, 2020). "LncRNA LINC00163 serves as the tumor suppressor through transcriptionally up-regulating TCF21 expression in inhibiting the development of lung cancer." (PMID 33014809, 2020). "TCF21 also acts as a tumor suppressors in multiple tumors, such as renal tumors, ovarian cancer, colorectal cancer, and lung cancer, among others." (PMID 31143705, 2019). "Herein, we aimed to investigate the inhibitory role of curcumin in lung cancer, with particular interest in the link between curcumin and TCF21 expression." (PMID 27894084, 2016).
lung carcinoma (continued). "RT-PCR analysis indicated that downregulation of TCF21 was a characteristic of aggressive lung cancer, and the TCF21 levels were inversely correlated with the aggressiveness of cancer cells (aggressiveness: BEAS-2B < A549 < PC9 < H1299)." (PMID 27894084, 2016). "Provided that TCF21 downregulation is an indicator of malignant lung cancer, we next investigated how TCF21 overexpression and knockdown would alter the growth of cancer cells." (PMID 27894084, 2016). "Analysis using the GEO database (access #GSE21210) indicated that a positive correlation existed between TCF21 levels and lung cancer patient survival." (PMID 27894084, 2016). "TCF21 protein expression was confirmed to be reduced in lung cancer cells." (PMID 40226362, 2025). "TCF21 (transcription factor 21) is a tumor suppressor gene that is methylated and downregulated in lung cancer and is related to cell viability, proliferation, apoptosis, and growth, as well as angiogenesis, epithelial–mesenchymal transition, tissue invasion, and metastasis." (PMID 36661515, 2023). "Moreover, lung cancer patients with elevated expression of TCF21, NKX2-1, TBX2, and TBX5 exhibited a decreased rate of survival relative to patients with low gene expression." (PMID 37627195, 2023). "Curcumin inhibits lung cancer by up-regulating TCF21 in EVs." (PMID 36569896, 2022). "Taken together, EGR1 is potentially involved in transcriptional regulation of TCF21 and the methylation states of EGR1 binding motif may influence the ability of EGR1 or WT1 to bind to TCF21 in lung cancer." (PMID 33859751, 2021). "In addition, the ability of TCF21 to regulate mesenchymal-epithelial transition is lost in lung carcinomas." (PMID 33729392, 2021). "A study has shown that decreased mRNA expression of TCF21, a tumor suppressor, is a core predictor for poor prognosis in patients with lung cancers in two studies, agree with what we found the prognosis association from TCGA LUAD with gene set “CUI_TCF21_TARGETS_2_UP” (P = 1.30 × 10− 4)." (PMID 30577835, 2018). "In addition, upregulating TCF21 expression is a viable strategy for suppressing lung cancer progression." (PMID 27894084, 2016). "TCF21 was reported to inhibit the proliferation and invasion of lung cancer cells." (PMID 27028856, 2016). "In lung cancer cell lines and head and neck squamous cell carcinoma cell lines, TCF21 expression could be restored through treatment with decitabine, one of the clinically available demethylating agents." (PMID 26158413, 2015). "OPCML, TNFRSF25 and TCF21 have been previously reported to be hypermethylated in lung cancer and based on their function, methylation-induced silencing could favor tumor growth." (PMID 18616821, 2008). "The short segment may account for the TCF21 expression abnormality in lung cancer." (PMID 28830341, 2017). "However, studies on TCF21 as a biomarker in lung cancer are still rare." (PMID 27894084, 2016). "Twelve of 20 genes (60%) in the list were methylation driver genes described previously in lung cancer, such as CDO1, SLIT2, SOX17 and TCF21." (PMID 33859751, 2021). "Three genes related to lung cancer were screened: Gremlin, fragile histidine triad (FHIT), and transcription factor 21 (TCF21)." (PMID 28811522, 2017). "Of 30 top ranked genes, FAM107A, MAMDC2, SOX17, TCF21, PTPRH, and CDO1 have been previously reported with aberrant DNA methylation in lung cancer." (PMID 27610367, 2016). "Two of the most frequently dysregulated transcription factors are co-expressed in lung cancer and PAH (FOXM1 and FOXF1), while the other six frequently deregulated transcription factors are co-expressed only in lung cancer (TCF21, SOX17, TAL1, LMO2, KLF2, and TBX4)." (PMID 36661515, 2023). "The transcription factor TCF21 has been reported to be more highly methylated in lung cancer tissue than non-tumor adjacent lung, and overexpression in mouse xenografts results in a reduction in tumor size and weight." (PMID 18616821, 2008).
lung carcinoma (continued). "However, high expression of ADAMTS8, CD36, DPYSL2, PLEKHH2, STX11, and TCF21 tends to lead to better prognosis, which coincides with the difference in expression of these HUB genes in normal samples and lung cancer samples." (PMID 37409245, 2023). "Moreover, FOXF1 is also co-expressed in the CCP of the LC RNA-Seq datasets, along with seven of the most frequently dysregulated TFs (FOXM1, SOX17, TAL1, TCF21, TBX4, LMO2, and KLF2), suggesting its importance as a regulator of gene expression during lung cancer progression." (PMID 36661515, 2023). "To confirm that TCF21 is a prognostic biomarker in lung cancer patients, we examined the NCBI GEO database (access #GSE31210), which contains a large number of expression profiles of lung cancer patients, in search for correlation between TCF21 and patient survival." (PMID 27894084, 2016).
coronary artery disease (25 papers, 2012 to 2025). "Transcription factor 21 (TCF21), a basic-helix-loop-helix transcription factor that contributes to the risk of coronary heart disease, blocks the MYOCD-SRF pathway via direct TCF21-MYOCD interaction and results in a less differentiated phenotype." (PMID 36604627, 2023). "This study showed that TCF21 (a causal coronary artery disease gene) was specifically upregulated in SMCs during phenotypic regulation." (PMID 36267275, 2022). "In a previous study, TCF21 was found to be associated with coronary heart disease, enhancing the “fibromyocyte” phenotype of smooth muscle cells." (PMID 33033240, 2020). "Variants within TARID or its target (ie TCF21) are associated with coronary artery disease, blood pressure, cis-effects on circulating cytokines, and visceral fat." (PMID 31622379, 2019). "The authors concluded that sinceTcf21 was associated with reduced risk of coronary artery disease, and that Tcf21 expression increased phenotypic modulation, phenotypic modulation is most likely associated with reduced coronary artery disease." (PMID 31921894, 2019). "Identification of Tcf21 as a pro-phenotypic modulator which was associated with protection from coronary artery disease." (PMID 31921894, 2019). "For example, SNP rs12190287 in the 3′UTR of transcription factor 21 (TCF21) is a coronary artery disease risk variant identified by GWAS." (PMID 25877638, 2015). "Together, these data suggest that miR-224 interaction with the TCF21 transcript contributes to allelic imbalance of this gene, thus partly explaining the genetic risk for coronary heart disease associated at 6q23.2." (PMID 24676100, 2014). "Together these findings provide additional mechanistic insights into the TCF21 association with respect to coronary heart disease progression." (PMID 24676100, 2014). "We performed a look-up of 25 validated SNPs for coronary heart disease from the CARDIoGRAM consortium, and found that rs12190287 at TCF21 was associated with pericardial fat in a direction-consistent fashion (p = 0.0019)." (PMID 22589742, 2012). "Our findings are also notable for some enrichment of association with a SNP in TCF21, previously identified in association with coronary heart disease in CARDIoGRAM." (PMID 22589742, 2012). "Moreover, SRF-myocardin axis has been shown to be antagonized by the over-expression of the coronary artery disease-risk gene Tcf21 in vivo." (PMID 41246212, 2025). "This study aimed to explore whether TCF21 gene (12190287G/C) variants affect coronary artery disease risk." (PMID 38250610, 2024). "In addition, evidences have suggested that TCF21 gene is required for cardiac fibroblast development, and the abnormal expression of TCF21 is associated with increased risk of coronary artery disease." (PMID 31354385, 2019). "The data suggest that TCF21 may have a role in regulating the differentiation state of SMC precursor cells that migrate into vascular lesions and contribute to the fibrous cap, and the TCF21 gene contributes to coronary artery disease (CAD) risk." (PMID 31354385, 2019). "Here, we show that a common heritable variation in the gene TCF21 may regulate coronary heart disease risk by regulating the response of downstream gene activation by the disease environment." (PMID 28481916, 2017). "Some literature reports 13 susceptible sites are detected in a GWAS on human coronary heart disease, among which rs12190287 is located at the 3’UTR of TCF21." (PMID 35158719, 2022). "Heterozygosity at coronary disease causal variation, or genome editing of these variants, is associated with decreased binding of both JUN and TCF21 and loss of expression in cis, supporting a transcriptional mechanism for disease risk." (PMID 31014396, 2019). "We show here that TCF21 and JUN regulate expression of two presumptive causal coronary disease genes, SMAD3 and CDKN2B-AS1, in part by interactions with histone deacetylases and acetyltransferases." (PMID 31014396, 2019).
coronary artery disease (continued). "In humans and mice, TCF21 is known to play an important role in diseases such as hypertension, gastric cancer, and coronary heart disease." (PMID 28235410, 2017). "In our study, TCF21, as the downstream target of miR-30-5p confirmed by the luciferase report assay in our study, was reported to be involved in the transcriptional network linking coronary heart disease and playing a crucial role in cardiac fibrosis and smooth muscle cell fate in atherosclerosis." (PMID 31354385, 2019). "Furthermore, TCF21 expression was closely related to regulation of the SMC phenotype in human diseased coronary arteries, and increased TCF21 expression was associated with a reduced risk of coronary artery disease in human coronary artery disease-associated tissues." (PMID 36267275, 2022). "Genome-wide TCF21 and JUN binding is jointly localized and particularly enriched in coronary disease loci where they broadly modulate H3K27Ac and chromatin state changes linked to disease-related processes in vascular cells." (PMID 31014396, 2019). "After intersection of AHR with ARNT and TCF21 the only remaining categories were coronary artery disease and coronary artery calcification, narrowing the importance of the interaction of AHR/ARNT and TCF21 factors to pathophysiological processes in cardiovascular disease." (PMID 28481916, 2017).